STRN (striatin)
Diseases named in the same sentence as STRN in open-access papers (continued):
Sharing a sentence is not in itself a finding about the gene and the disease.
type-2 diabetes (1 paper, 2019). "COX proportional hazards regression analysis confirmed that MT-COI and STRN, but not COX10, were independently related to time to new event adjusting for age, gender, (ex)-smoking, BMI, blood pressure, type-2 diabetes, HDL- and LDL-cholesterol, triglycerides and hs-C-reactive protein." (PMID 31821324, 2019).
cancer (21 papers, 2012 to 2025). A tumor composed of atypical neoplastic, often pleomorphic cells that invade other tissues. "STRN has multiple functional signaling complexes which are reportedly involved in the tumorigenesis of various cancers." (PMID 37950349, 2024). "Increased expression of STRN was found in different cancers, which induced cell cycle progression and invasiveness by activating downstream transcription factors, including misshapen-like kinase 1, RhoA, TRAF2, NCK-interacting protein kinase and PDGFRA." (PMID 38215077, 2024). "STRN was mainly located in the cytoplasm of cancer cells and was highly expressed in human HCC tissues, with a positive rate of high expression of 51.1% (23/45)." (PMID 32280692, 2020). "Interestingly, depletion of the striatin STRN3 in human A431 carcinoma cells led to a similar phenotype to FAM40A depletion, indicating that they act on the same pathway." (PMID 30509168, 2018). "In the present study, we revealed that STRN may promote HCC invasion and migration but does not significantly affect cell proliferation or apoptosis, strengthening the support for the important but complicated role of STRN in the development of malignant tumours." (PMID 32280692, 2020). "This epidemiologic distribution of ALK rearrangement was confirmed in more recent studies, all representing by striatin (STRN)-ALK fusion, an extremely rare ALK rearrangement reported in only 56 cancers of different organs." (PMID 35223506, 2022). "The hub genes (PIK3CA, STRN, C9orf102, REST, and NHLRC2) obtained from LinkedOmics were submitted to GSCALite for cancer pathway activity and drug sensitivity analysis." (PMID 34367282, 2021). "Additionally, we analyzed the top 100 genes coexpressed with SELENOI across 33 cancer types using GEPIA2.0, and identified PUM2, STRN, WDR43, PRPF40A, and SPAST as highly correlated with SELENOI." (PMID 39669976, 2024). "Moreover, we also conducted cancer pathway activity and drug sensitivity analysis of hub genes (PIK3CA, STRN, C9orf102, REST, and NHLRC2) obtained from LinkedOmics." (PMID 34367282, 2021). "In another cancer-originating cell line, striatin was found to localize with TJ proteins but not with the AJ protein E-cadherin." (PMID 32766247, 2020). "The other five genes (TMEM33, UBE2H, ATAB2D, ZBT44 and STRN) were not reported in cancers." (PMID 37407973, 2023). "This highlights the heterogeneity of STRN‐ALK fusion in response to ALK inhibitors, and could be crucial to help guide therapeutic decisions to achieve maximum benefit in the era of personalized cancer therapy." (PMID 33960639, 2021). "In three different human cancer-originating epithelial cell lines, Caco2 and CFAPAC-1, striatin co-localizes with the TJ marker ZO-1 but not with the AJ protein-β-catenin." (PMID 32766247, 2020).
tumor (14 papers, 2016 to 2024). "Upstream control of MAP4K4 in tumor cells is exerted by striatin (STRN) family proteins (members of the STRIPAK family)." (PMID 37223681, 2023). "Interestingly, the increase in Striatin expression has been shown to correlate to the cellular reprogramming event, the epithelial to mesenchymal transition, which has been implicated in promoting tumor initiation and metastasis in a variety of epithelial-based cancers." (PMID 36328247, 2022). "Previous studies showed aggressive features of tumours with STRN‐ALK fusion including lymph node metastasis and extraorgan extension." (PMID 34541785, 2021). "The relationship between STRN and tumours has attracted researchers' attentions in recent years." (PMID 32280692, 2020). "However, a decrease in tumour cell invasion and migration capacities could be observed by transwell invasion and wound healing assays, upon STRN inhibition." (PMID 32280692, 2020). "Three of the studies investigated reported on tumor tissue vs non-tumor tissue (GSE15471, GSE16515 and GSE101448), and in all these, we found an upregulation of KIAA1524/CIP2A, TIPRL, STRN and ARPP19, and a reduced expression of PPP2R1B in the tumor." (PMID 37170215, 2023). "Proteins encoded by PP2A genes identified to be highly correlating with aggressive PDAC in GSE62165 were also significantly different between normal tissue and PDAC tumor, with again CIP2A, TIPRL and STRN as top altered hits." (PMID 37170215, 2023). "Our results suggest that STRN is upregulated in HCC tissues and cells and acts as a tumour promoter regulating cell invasion and migration through facilitating the EMT process." (PMID 32280692, 2020). "In summary, the present investigation revealed that STRN was aberrantly overexpressed in HCC tissues and positively correlated with tumour lymph node metastasis and clinical stage." (PMID 32280692, 2020). "Taken together, STRN is upregulated in HCC and acts as a tumour promoter regulating cell invasion and migration through facilitating the EMT process." (PMID 32280692, 2020). "Rearrangements involving the anaplastic lymphoma kinase (ALK) gene with the striatin (STRN) gene have been described, which constitutively activate ALK kinase, inducing tumor formation in nude mice." (PMID 31717449, 2019). "Among the most frequent 5′-partners are EML4 (echinoderm microtubule-associated protein-like 4) in NSCLC and STRN (striatin), NPM1 (nucleophosmin), and TPM3 (tropomyscin 3) in non-NSCLC neoplasms." (PMID 39594806, 2024). "Functionally, gene fusion involving STRN leads to constitutive activation of ALK kinase via dimerization mediated by the 5′ coiled-coil domain in the gene, while investigation of the role of the gene itself in tumour progression was neglected in most studies." (PMID 32280692, 2020). "Since the migration and invasion of tumour cells are closely related to EMT, we further investigated whether STRN has the potential to affect EMT in HCC cells." (PMID 32280692, 2020). "In vitro, high expression of STRN was also confirmed in different HCC cell lines, and regulation of STRN expression in Huh7 cells did not significantly affect tumour cell proliferation or apoptosis but was positively correlated with tumour cell invasion and migration capacities." (PMID 32280692, 2020). "Notably, STRN protein expression was not correlated with tumour size or histological classification, consistent with the observation that the regulation of STRN expression in vitro did not significantly affect the proliferation or apoptosis of Huh7 cells." (PMID 32280692, 2020).
cardiac diseases (1 paper, 2015). "Furthermore, the STRN genotype may influence the severity or manifestation of other cardiac diseases." (PMID 25661582, 2015).
cardiovascular disorder (1 paper, 2024). A disease involving the cardiovascular system. "Consistently, the loss of striatin from the intercalated discs, along with the appearance of compromised desmosomal structures, were documented in cardiovascular disorders namely in patients suffering from DCM." (PMID 38579991, 2024).
infection (1 paper, 2023). The state of being infected such as from the introduction of a foreign agent such as serum, vaccine, antigenic substance or organism. "Binding of STRN and STRN3 to the M1 protein was also observed by a complementary experimental approach using co-IP after infection of human 293T cells or murine MLE-15 cells with SC35M viruses." (PMID 36602306, 2023).
STRN also shares sentences with these, for which no sentence is quoted: cardiomyopathy (2 papers); dilated cardiomyopathy (2); lymph node metastasis (2); peritoneal mesothelioma (2); Anxiety (1); Arrhythmia (1); Cirrhosis (1); colon adenocarcinoma (1); coronary artery disease (1); diabetes (1); fibrosarcoma (1); glioneuronal tumor (1); Headache (1); Hepatitis (1); hypertensive heart disease (1); ischemic cardiomyopathy (1); large cell lymphomas (1); lipoma (1); papillary thyroid cancer (1); renal cell carcinoma (1); Stroke (1); thyroid (1); Ventricular arrhythmia (1).